SLC35E1 (solute carrier family 35 member E1)
Description:
Putative transporter.
Synonyms: FLJ14251
Tractability: Antibody: UniProt predicts a signal peptide or a membrane-spanning region. PROTAC: ubiquitination databases record sites on it; its protein half-life has been measured.
Gene: Protein-coding gene on chromosome 19 (16,549,831 to 16,572,415, reverse strand). Ensembl gene ENSG00000127526.
Subcellular location: Membrane
Subcellular location (Human Protein Atlas): Golgi apparatus
Gene Ontology:
Molecular function: protein binding
Cellular component: Golgi apparatus; membrane
Genetic constraint (gnomAD): Loss-of-function variants: 14 observed, 32.25 expected, observed/expected ratio (o/e) 0.43, 90% interval 0.29 to 0.68. The upper end of that interval is the gene's LOEUF score, 0.68, which puts it in group 2 of 6, group 1 being the genes least tolerant of losing a copy. Missense variants: 429 observed, 541.28 expected, observed/expected ratio (o/e) 0.79, 90% interval 0.73 to 0.86. Synonymous variants: 257 observed, 248.28 expected, observed/expected ratio (o/e) 1.04, 90% interval 0.93 to 1.15.
Homologues: Orthologues: chimpanzee SLC35E1 (100% identical), macaque SLC35E1 (99% identical), pig SLC35E1 (97% identical), dog SLC35E1 (96% identical), rat Slc35e1 (91% identical), mouse Slc35e1 (91% identical), zebrafish slc35e1 (65% identical), guinea pig SLC35E1 (65% identical), Drosophila melanogaster CG14621 (40% identical). Paralogues in human: SLC35E2B (25% identical), SLC35D3 (14% identical), SLC35E3 (14% identical), SLC35E4 (13% identical), SLC35C1 (13% identical), SLC35D2 (12% identical), SLC35H1 (12% identical), SLC35D1 (11% identical), SLC35D4 (9% identical).
Diseases named in the same sentence as SLC35E1 in open-access papers:
SLC35E1 is named in the same sentence as 6 diseases in open-access papers, as found by Europe PMC text mining. Sharing a sentence is not in itself a finding about the gene and the disease. The quoted sentences say what the papers report.
endometrial cancer (1 paper, 2019). Primary or metastatic malignant neoplasm involving the endometrium (mucous membrane that lines the endometrial cavity). "Another gene found to be associated with endometrial cancer in this study, SLC35E1 is known to be upregulated in late-stage endometrial endometrioid carcinoma." (PMID 31338326, 2019). "Seven genes, including RBM12, NDUFB6, ATP6V1A, RECK, SLC35E1, RFX3 (Bonferroni-corrected P < 0.05) and ATP8A1 (suggestive P < 10−5), and one long non-coding RNA, DLGAP4-AS1 (Bonferroni-corrected P < 0.05), were associated with endometrial cancer." (PMID 31338326, 2019). "The SLC35E1 is not well-studied, and its mechanism of action in endometrial cancer is not well-understood." (PMID 31338326, 2019).
psoriasis (1 paper, 2023). An autoimmune condition characterized by red, well-delineated plaques with silvery scales that are usually on the extensor surfaces and scalp. "SLC35E1 deficiency inhibited keratinocyte proliferation in mice with imiquimod (IMQ)-induced psoriasis." (PMID 37296095, 2023). "In addition to the association with psoriasis, we observed that Slc35e1−/− mice have significantly lower body weight than their WT siblings, suggesting that SLC35E1 may also play a role in development." (PMID 37296095, 2023). "We observed that SLC35E1 was highly enriched in the suprabasal layer of psoriasis lesions, but was ubiquitously distributed in the basal layer of the epidermis in the controls." (PMID 37296095, 2023). "To investigate the function of SLC35E1 in the pathogenesis of psoriasis, we established a mouse model of psoriasis in Slc35e1−/− mice via the topical application of IMQ, with their WT siblings serving as controls." (PMID 37296095, 2023). "To gain insight into the expression profile of SLC35E1 in psoriatic lesions, we performed an immunohistochemical analysis of SLC35E1 in skin samples from patients with psoriasis and healthy controls." (PMID 37296095, 2023). "Our results indicated that SLC35E1 can promote keratinocyte proliferation by regulating zinc ion homeostasis and zinc ion supplementation has potential as a therapy for psoriasis." (PMID 37296095, 2023). "Consistent with this, immunoblotting and qPCR analysis showed that the protein and mRNA expression of SLC35E1 was significantly increased in psoriasis lesions compared with that in healthy skin." (PMID 37296095, 2023). "In IMQ mouse model of psoriasis, the phenotype of SLC35E1 was rescued by reducing the concentration of zinc ions." (PMID 37296095, 2023). "Here, we investigated the contribution of SLC35E1 to keratinocyte hyperproliferation in psoriasis." (PMID 37296095, 2023). "It remains that SLC35E1 reduces zinc ion concentration to promote psoriasis in keratinocytes." (PMID 37296095, 2023). "We further showed that the role of SLC35E1 in psoriasis is to regulate zinc ion homeostasis." (PMID 37296095, 2023). "Our findings suggested that SLC35E1 may promote keratinocyte proliferation by regulating zinc levels, an effect that may be related to the pathogenesis of psoriasis." (PMID 37296095, 2023). "Here, we found that SLC35E1 was highly expressed in keratinocytes of patients with psoriasis and that Slc35e1−/− mice displayed a less severe imiquimod (IMQ)-induced psoriasis-like phenotype than their wild-type siblings." (PMID 37296095, 2023). "Analysis of the GSE121212 dataset indicated that SLC35E1 expression was significantly higher in non-lesional psoriatic skin than in the skin of healthy controls, and was also higher in psoriatic lesions than in non-lesional psoriatic skin from the same psoriasis patients." (PMID 37296095, 2023).
cancer (1 paper, 2019). A tumor composed of atypical neoplastic, often pleomorphic cells that invade other tissues. "Three variants in RBM12, one variant in NDUFB6, ten variants in DLGAP4-AS1, five variants in ATPV1A, eleven variants in RECK, four variants in SLC35E1, eight variants in RFX3, and eight variants in ATP8A1 were known somatically acquired mutations in various cancers." (PMID 31338326, 2019).
SLC35E1 also shares sentences with these, for which no sentence is quoted: colorectal cancer (1 paper); endometrial endometrioid carcinoma (1); infection (1).